Y_RNA (Y RNA )
Gene: Miscellaneous RNA gene on chromosome 2 (166,123,494 to 166,123,597, reverse strand). Ensembl gene ENSG00000238813.
Homologues: Orthologues: chimpanzee Y_RNA (97% identical), macaque Y_RNA (91% identical), guinea pig Y_RNA (89% identical), guinea pig Y_RNA (88% identical), rat Y_RNA (87% identical). Paralogues in human: Y_RNA (91% identical), RNY1 (90% identical), RNY1P11 (89% identical), Y_RNA (88% identical), Y_RNA (87% identical), Y_RNA (86% identical), Y_RNA (85% identical), RNY1P8 (84% identical), Y_RNA (84% identical), RNY1P10 (83% identical), RNY1P13 (83% identical), Y_RNA (83% identical), and 100 more.